HNF4A (hepatocyte nuclear factor 4 alpha)
Diseases named in the same sentence as HNF4A in open-access papers (continued):
Sharing a sentence is not in itself a finding about the gene and the disease.
Glucose intolerance (6 papers, 2010 to 2025). Glucose intolerance (GI) can be defined as dysglycemia that comprises both prediabetes and diabetes. "In keeping with previous studies of mice with β-cell specific ablation of Hnf4a (Hnf4abetaKO), Hnf4apKO mice developed a mild complex phenotype, with very subtle glucose intolerance and a slightly reduced fasting glycemia." (PMID 20523905, 2010). "Similarly, the glucose intolerance observed in the HFD fed mice was more prominent in the mice which lack the HNF4α in the β-cells." (PMID 39741884, 2024). "From our data, it is plausible that incretin response might be impaired and contributory to glucose intolerance in the preclinical stages in some patients with HNF4A MODY." (PMID 24299156, 2014). "Thus, although male and female mice with beta cell-specific HNF4α knockout (MKO and FKO, respectively) become hyperglycemic, only MKO mice have worsening glucose intolerance dependent on age." (PMID 41017587, 2025). "Of note, HNF4A regulates the expression of HNF1A and is therefore expected that, with the exception of normoglycemic glycosuria, the HNF4A-MODY phenotype is similar to that of HNF1A-MODY, with glucose intolerance becoming evident during adolescence or early adulthood and deteriorating with age." (PMID 35052457, 2022).
hemophilia (6 papers, 2009 to 2023). Hemophilia is a genetic disorder characterized by spontaneous hemorrhage or prolonged bleeding due to factor VIII or IX deficiency. "Mutations of HNF4α and HNF4α response elements cause maturity-onset diabetes of the young 1 (MODY1), a rare disease; certain types of hemophilia; and hepatitis B viral infections." (PMID 37079387, 2023).
neuroblastoma (6 papers, 2020 to 2023). Neuroblastoma (NB) is the most common solid, extracranial childhood tumor. "A recent analysis of clinical neuroblastoma tissue samples revealed that HNF4α promoted the invasion, metastasis, and angiogenesis of neuroblastoma cells by targeting matrix metalloproteinase 1456." (PMID 33462379, 2021). "Overexpression of HNF4α can enhance the aggressiveness and angiogenesis of neuroblastoma cells via its direct upregulation of matrix metalloproteinase 14 (MMP-14)." (PMID 31695151, 2020). "Moreover, Li and Chen57 reported that the overexpression of miR-34a inhibits the proliferation, migration, and invasion of human neuroblastoma SH-SY5Y cells by targeting HNF4α." (PMID 33462379, 2021). "However, in neuroblastoma, a pediatric solid tumor miR-34a appears to play anti-oncogenic role, while also regulating levels of HNF4α." (PMID 34771521, 2021). "In neuroblastoma, HNRNPU activates the CCCTC-binding factor (CTCF) by binding to hepatocyte nuclear factor 4 alpha (HNF4A)-derived long noncoding RNA (HNF4A-AS1)." (PMID 36012592, 2022). "HNF4α is also involved in the axis with miR-542-3p and lncRNA, SNHG16 in neuroblastoma." (PMID 34771521, 2021).
viral infection (6 papers, 2011 to 2025). "While its metabolic roles are well-established, Hnf4α’s function in bacterial infection, viral infection, and bacterial-viral coinfection—major challenges in global aquaculture—remained uncharacterized." (PMID 40920830, 2025). "Many of these transcription factors, such as NF-κB, STAT3, and HNF4A, are known to be activated in response to viral infections and inflammation." (PMID 40408617, 2025). "Although the expression of miR-122 is transcriptionally regulated by liver-enriched transcription factors, including hepatocyte nuclear factor 4 alpha (HNF4) and C/EBPα, it may also be regulated by viral infection." (PMID 36142450, 2022).
chronic kidney disease (5 papers, 2019 to 2025). Impairment of the renal function secondary to chronic kidney damage persisting for three or more months. "Genetic heterogeneity at the HNF4A locus results in different genetic variants that confer risk for both hyperuricemia and chronic kidney disease, hinting at the involvement of distinct pathways." (PMID 40430440, 2025). "Loss of HNF4A expression and gain of vimentin expression were reciprocal and gradual during both acute and chronic kidney disease, as indicated by immunohistochemistry." (PMID 39954965, 2025). "Importantly, HNF4α is also associated with coronary artery calcification in the Chronic Renal Insufficiency Cohort and with osteoporosis in the Framingham Osteoporosis Study, which was mostly attributed to HNF4α function in liver and kidney." (PMID 37079387, 2023). "During chronic kidney disease, stretches of cells with loss of HNF4A could be observed." (PMID 39954965, 2025). "This study demonstrated that partial, or more often, complete depletion of the transcription factor HNF4A characterizes a range of acute and chronic kidney diseases." (PMID 39954965, 2025). "Thus, the reduction of HNF4A and increase of vimentin expression were connected to both acute and chronic kidney disease and represented a stereotypic injury response of the PT, resulting in dedifferentiation." (PMID 39954965, 2025). "Notably, expression of megalin (LRP2), an endocytic receptor of various molecules involved in development and progression of chronic kidney disease (CKD), was strongly induced by HNF4α, and the transactivation potential of the megalin promoter was dependent on HNF4α expression." (PMID 30582012, 2019).
clear cell renal cell carcinoma (5 papers, 2015 to 2023). "Specifically, ALDH6A1 is regulated by a well‐known suppressor transcription factor HNF4A, which suppressed tumorigenic capability in clear renal cell carcinoma." (PMID 37395176, 2023). "ALDH6A1, as a potential target gene of HNF4A, could suppress the proliferation and metastasis of clear renal cell carcinoma (ccRCC)." (PMID 36098688, 2022). "Focusing on this discrepancy, we use changes in co-expression patterns to highlight the apparent loss of regulation by the transcription factor HNF4A in clear cell renal cell carcinoma, despite no differential expression of HNF4A." (PMID 25961905, 2015). "In renal clear cell carcinoma, low-expressed ABAT promoted tumor development by boosting cancer cells' metabolism, which the transcription factor HNF4A may regulate." (PMID 34539973, 2021).
colorectal adenocarcinoma (5 papers, 2018 to 2025). The most common type of colorectal carcinoma. "During the differentiation of human epithelial colorectal adenocarcinoma cells (Caco2), phosphorylated RNA pol II was found to be assembled within a pre-initiation complex prior to recruiting HNF4A." (PMID 30597922, 2018). "Hepatocyte nuclear factor 4α (HNF4α), a highly conserved member of the nuclear receptor superfamily of transcription factors, has been identified as a promising therapeutic candidate for colorectal adenocarcinoma (CRAC)." (PMID 40277924, 2025). "In contrast to HCC, where an overall diminished HNF4A signaling is observed in most studies several gastrointestinal adenocarcinomas (GIAC) including esophageal, gastric, pancreatic, and colorectal adenocarcinomas are characterized by increased HNF4A expression." (PMID 32998360, 2020). "However, Caco2 is an epithelial cell line isolated from a colorectal adenocarcinoma and so it was unclear whether the action of HNF4A would be the same during the formation of hepatic progenitor cells." (PMID 30597922, 2018).
COVID-19 (5 papers, 2022 to 2025). A disease caused by infection with severe acute respiratory syndrome coronavirus 2. "Gastrointestinal symptoms of varying severity are noted in subsets of COVID-19 patients, and may be associated with variation in HNF4A in them." (PMID 36143338, 2022). "HNF4A influences immune responses and cytokine expression in COVID-19, contributing to liver damage and dysfunction." (PMID 40408617, 2025).
endometriosis (5 papers, 2018 to 2025). The growth of functional endometrial tissue in anatomic sites outside the uterine body. "This unexpected finding requires further validation to identify the underlying mechanism mediated by HNF4A in endometriosis." (PMID 29357938, 2018). "In order to explore the effect of the HDAC2/HNF4A axis on endometriosis cells, HDAC2 and HNF4A were silenced in the endometriosis cell line hEM15A alone or in combination." (PMID 34586697, 2021). "In order to confirm that the downstream gene was endometriosis‐related gene, the Pearson correlation between HNF4A and other genes in endometriosis samples of GSE37837 was analysed, which screened out 7265 genes with |cor| > 0.8 and p < 0.05." (PMID 34586697, 2021). "Further ChIP analysis documented that HDAC2 increased significantly in the promoter region of HNF4A in endometriosis tissues compared with normal tissues." (PMID 34586697, 2021). "Corroborating finding are identified in a previous study, which demonstrated that HNF4A is involved in the pathogenesis of endometriosis." (PMID 34586697, 2021). "Notably, several studies report decreased levels of proteins such as LIF, ARID1A (AT-rich interaction domain 1A), and HNF4A (hepatocyte nuclear factor 4 alpha) in the endometriosis tissues." (PMID 40649777, 2025). "Importantly, it was depicted in a prior research that HDAC2 overexpression augmented the deacetylation of HNF4A during Alzheimer's disease, which partially supported our results that HDAC2 repressed HNF4A expression through deacetylation during endometriosis." (PMID 34586697, 2021). "Therefore, this study was designed to explore the mechanism of HDAC2 orchestrating hepatocyte nuclear factor 4α/AT‐rich interactive domain 1A (HNF4A/ARID1A) axis in endometriosis." (PMID 34586697, 2021). "Moreover, our data further ascertained that HNF4A was downregulated in endometriosis tissues and that HNF4A silencing enhanced hEM15A cell proliferation and invasion but blocked cell apoptosis." (PMID 34586697, 2021). "Then, we explored the downstream mechanism of HNF4A in endometriosis." (PMID 34586697, 2021). "Moreover, Western blot analysis and immunohistochemistry depicted that the expression of HNF4A protein in endometriosis tissues was significantly lower than that in normal tissues." (PMID 34586697, 2021). "Collectively, silencing HDAC2 could repress the proliferation and invasion and augmented the apoptosis of endometriosis cells by upregulating HNF4A." (PMID 34586697, 2021). "Specifically, some key regulators from the miR-449 and miR-34b/c cluster, miR-200 family, miR-106a-363 cluster, miR-182/183, FOX family, GATA family, and E2F family as well as CEBPA, SOX9 and HNF4A were suggested to play vital regulatory roles in the pathogenesis of endometriosis." (PMID 29357938, 2018). "Importantly, the involvement of HNF4A has been noted in the pathogenesis of endometriosis." (PMID 34586697, 2021). "Notably, the integrative data revealed that HNF4A targets 12 miRNAs and thus might be a miRNA “hub” in endometriosis." (PMID 29357938, 2018). "Correlation map drawn based on analysis in microarray dataset GSE37837 revealed a positive correlation between HNF4A and ARID1A expression in endometriosis tissues." (PMID 34586697, 2021). "Conclusively, the activation of the HNF4A/ARID1A axis inhibited the proliferation and invasion and promoted the apoptosis of endometriosis cells." (PMID 34586697, 2021). "In order to explore the effect of HDAC2 on the expression of HNF4A during endometriosis, we first found a significant negative correlation between HDAC2 and HNF4A expression in endometriosis by GSE37837." (PMID 34586697, 2021). "In this context, we speculated that the network of HDAC2, HNF4A and ARID1A might be correlated with the pathogenesis of endometriosis." (PMID 34586697, 2021). "Collectively, HDAC2 silencing might upregulate HNF4A via repression of deacetylation to activate ARID1A, thus preventing the occurrence of endometriosis." (PMID 34586697, 2021).
endometriosis (continued). "HDAC2 was upregulated but HNF4A and ARID1A were downregulated in endometriosis tissues." (PMID 34586697, 2021). "Consequently, our data unravelled that silencing HDAC2 increased HNF4A expression through inhibition of deacetylation to upregulate ARID1A, thus preventing endometriosis." (PMID 34586697, 2021).
glioma (5 papers, 2011 to 2026). A benign or malignant brain and spinal cord tumor that arises from glial cells (astrocytes, oligodendrocytes, ependymal cells). "Expression of HNF4α was higher in tumors samples than controls; Huntingtin and c-Myc were found to be overexpressed in high-grade gliomas." (PMID 25050814, 2014). "In high-grade gliomas 14-3-3ζ and HNF4α were strongly expressed in nuclear and cytoplasmatic compartments." (PMID 25050814, 2014). "14-3-3ζ, HNF4α and Huntingtin were widely expressed in glioma samples." (PMID 25050814, 2014). "In addition, Chromatin Immunoprecipitation (ChIP)-PCR analysis showed that HNF4A bound to the CHPF promoter region, which indicated that the transcription factor hepatocyte nuclear factor 4A (HNF4A) could regulate the expression of CHPF in glioma cells." (PMID 37851364, 2023). "However, the molecular mechanisms of HOXC11, HOXC9, ELF5, and HNF4A function in the development and progression of gliomas remain unclear and require further exploration in the future." (PMID 33503296, 2021). "CircVPS8 enhances glioma CSC viability, proliferation, and stemness, and suppresses ferroptosis by scaffolding MKRN1, SOX15, and HNF4A." (PMID 41601687, 2026). "In this study, we showed that HNF4A was enriched in the promoter region of CHPF and stimulated the expression of CHPF in glioma." (PMID 37851364, 2023). "The BTSCs also showed ⩾100-fold increase in the transcription of TLX and HNF4α, and between 10- and 100-fold increase in PXR, RORα, RORγ, NORI and LRH compared with glioma cells." (PMID 21224854, 2011). "However, no studies have characterized the molecular mechanisms of HNF4A in glioma." (PMID 37851364, 2023).
hepatitis B (5 papers, 2012 to 2022). "So it is reasonable to infer that the correlation of over-expression of HNF4α with severe hepatitis B may associate with its effect on HBV." (PMID 22257755, 2012). "The findings identified potential targets of interventional strategies for treating hepatitis B patients through manipulation of the IL-23 and HNF4α." (PMID 29983862, 2018). "In present study, we studied the variation of HNF4α and HNF3β expression in different types of hepatitis B, so as to investigate the correlation of HNFs expression and disease severity." (PMID 22257755, 2012).
insulinoma (5 papers, 2009 to 2021). "In agreement, disrupting Hnf4a expression in mouse islets or insulinoma cells resulted in impaired glucose-stimulated insulin secretion." (PMID 34732735, 2021). "Since in HEK293 cells the HNF4A gene is silent, we measured the activity of the same 3′UTR fragments in the rat insulinoma cell line INS-1 expressing Hnf4a." (PMID 22140441, 2011).
lung adenocarcinoma (5 papers, 2021 to 2025). A carcinoma that arises from the lung and is characterized by the presence of malignant glandular epithelial cells. "Therefore, the expression of HNF4α has potential as a therapeutic target in lung adenocarcinomas, particularly KRAS-mutated lung adenocarcinomas." (PMID 38710944, 2025). "For all these reasons, HNF-4α is worthy of further studies since it might be considered a prognostic biological marker for IPF-associated lung adenocarcinoma and might be implicated in IPF molecular mechanisms." (PMID 36674438, 2023). "We also demonstrated that four lung adenocarcinoma cell lines (A549, H1651, H2405, and Calu-3) had high HNF4α expression at both the gene and protein levels." (PMID 38710944, 2025). "Immunohistochemical analysis was performed using xenograft tumors of lung adenocarcinoma cell lines with high HNF4A expression." (PMID 38710944, 2025). "We previously noted that the knockdown of HNF4A in lung adenocarcinoma cell lines suppressed the expression and phosphorylation of ERBB3 (data not shown)." (PMID 38710944, 2025). "HNF4α-positive grade 3 adenocarcinoma shows a very poor prognosis, and HNF4α expression is an independent prognostic factor in grade 3 lung adenocarcinomas." (PMID 38710944, 2025). "We conducted an immunohistochemical analysis of HNF4α using 241 primary lung adenocarcinoma samples surgically resected at Jichi Medical University Hospital and found that 33 samples (14%) were positive for HNF4α." (PMID 38710944, 2025). "HNF4α-positive cases among 241 lung adenocarcinomas were stratified based on TTF-1 and SMARCA4 expressions, histological subtypes, and driver mutations." (PMID 38710944, 2025). "Restoration of POR expression blocked the promoting effect of HNF4A on ferroptosis in lung adenocarcinoma." (PMID 37180584, 2023). "This study aims to investigate the function and mechanism of hepatic nuclear factor 4 alpha (HNF4A) in lung adenocarcinomas’ ferroptosis." (PMID 37180584, 2023). "In parallel, HNF4A knockdown increased the level of cellular lipid peroxidation in lung adenocarcinoma cells treated with ferroptosis inducers, while HNF4A overexpression had the opposite effect." (PMID 37180584, 2023). "To explore the function of HNF4A in ferroptosis, we sought to modify HNF4A expression in lung adenocarcinoma cells." (PMID 37180584, 2023). "We identified a key ferroptosis-related gene, POR serves as a potential target gene of HNF4A, whose expression was significantly changed in lung adenocarcinoma cells knocking down or overexpressing HNF4A." (PMID 37180584, 2023). "Also, our qRT-PCR and western blot results demonstrated that HNF4A knockdown significantly reduced POR expression whereas HNF4A overexpression promoted POR expression in lung adenocarcinoma cells." (PMID 37180584, 2023). "Promoting HNF4A-regulated ferroptosis may be beneficial in the clinical treatment of lung adenocarcinoma." (PMID 37180584, 2023). "We speculate that this is not because of the higher frequency of HNF4α-positive cases in Caucasians, but because of the higher frequency of KRAS mutations in HNF4α-negative adenocarcinomas (mainly TRU-type lung adenocarcinomas) in Caucasians." (PMID 38710944, 2025). "HNF4A promotes POR expression through binding to the POR’s promoter, and subsequently promotes the ferroptosis of lung adenocarcinoma." (PMID 37180584, 2023). "In this study, we discovered that a transcript factor called hepatocyte nuclear factor 4 alpha (HNF4A) dramatically increased cytochrome P450 oxidoreductase (POR), which in turn significantly accelerated ferroptosis in lung adenocarcinoma." (PMID 37180584, 2023). "To demonstrate that HNF4A promoted ferroptosis via POR in lung adenocarcinoma, we overexpressed POR in HNF4A-knockdown A549 cells, and knocked down POR expression in HNF4A-overexpressed H23 cells." (PMID 37180584, 2023).